ENSG00000291201 (novel transcript)
Gene: Long non-coding RNA gene on chromosome 4 (118,591,712 to 118,679,860, forward strand). Ensembl gene ENSG00000291201.
Gene Ontology:
Molecular function: U4 snRNA binding
Biological process: formation of quadruple SL/U4/U5/U6 snRNP; spliceosomal tri-snRNP complex assembly
Cellular component: U4/U6 x U5 tri-snRNP complex; U6 snRNP